STAT3 (signal transducer and activator of transcription 3)
Diseases named in the same sentence as STAT3 in open-access papers (continued):
Sharing a sentence is not in itself a finding about the gene and the disease.
multiple myeloma (continued). "Bavachin induces apoptosis by inhibiting the activation of NF-κB and STAT3 in multiple myeloma cell lines." (PMID 34539403, 2021). "Leelamine from pine’s bark attenuated phosphorylation of upstream JAK1/JAK2/Scr macromolecules and downstream STAT3, hence evoking myeloma cell cycle arrest and apoptosis." (PMID 34680295, 2021). "Resveratrol was found to inhibit IL-6-induced activation of STAT3 in human multiple myeloma cells and endothelial cells." (PMID 34564613, 2021). "Curcumin is reported as an inhibitor of p-STAT3, to abrogate the IL-6-induced phosphorylation of STAT3, and inhibits the proliferation and survival of multiple myeloma cells." (PMID 34337082, 2021). "In human multiple myeloma (MM) cells, constitutive and IL-6 inducible STAT3 activation are inhibited by inhibiting tyrosine kinases such as JAK1 and JAK2." (PMID 34539403, 2021). "In this regard, we have previously shown that STAT3 signaling was activated in myeloma cell lines cultured in 3D." (PMID 34201211, 2021). "Ko and colleagues reported that 3FC can display antiproliferative activity by impeding the STAT3 pathway in multiple myeloma cells." (PMID 35053027, 2021). "It has been shown to effectively suppress myeloma cell growth via Stat3 and Jak2 inhibition, and it has potential as a treatment for RA and other autoimmune diseases." (PMID 34680353, 2021). "Inhibition of tumor cell proliferation and reversal of chemotherapy resistance in multiple myeloma cells by blocking STAT3 activation." (PMID 34539403, 2021). "As a multitarget kinase inhibitor, AT-9283 can inhibit the process of STAT3 tyrosine phosphorylation and inhibit multiple myeloma cell proliferation and is widely used in cancer treatment." (PMID 34016786, 2021). "We next asked if the addition of IL6, a well-known STAT3 activating cytokine in myeloma, will help improve CD38+ cell viability." (PMID 34201211, 2021). "Inhibition of CK2 using CX-4945 resulted in decreased phospho-STAT3 levels in multiple myeloma and mantle cell lymphoma cells as well as suppression of STAT3 target genes (Cyclin D1, IL-6)." (PMID 34944749, 2021). "First, bioinformatic analyses of multiple myeloma identified CCT3 targeted genes that were involved in the JAK/STAT3 pathway." (PMID 34612768, 2021). "In keeping with this, we treated the bone marrow mononuclear cells from myeloma patients in 3D culture with two different doses of Stattic (0.4 and 4 μM) required to substantially bind to STAT3 in U266 cells cultured conventionally and in 3D, respectively." (PMID 34201211, 2021). "STAT3 constitutive activation is evident during the onset and progression of various cancers, including multiple myeloma, leukaemia, lymphomas and solid tumours." (PMID 33382511, 2021). "Abnormal suppression of SHP1/2 and SOCS-1 in multiple myeloma (MM) plasma cells significantly correlated with the sustained activation of the JAK/STAT3 pathway." (PMID 34680295, 2021). "In particular, guggulsterone abrogated the stimulation of c-Src and JAK2 and therefore inactivates STAT3 in human multiple myeloma cells." (PMID 32545187, 2020). "The survival of INA-6 human multiple myeloma cells is strictly dependent upon the Interleukin-6-activated transcription factor STAT3." (PMID 32041604, 2020). "Data also showed that deregulated STAT3 and STAT5 activity promotes drug resistance in leukemias/lymphomas/myelomas, highlighting the crucial interest to develop pharmacological molecules that selectively target STAT3 and/or STAT5 in hematologic cancers." (PMID 31963765, 2020). "In multiple myeloma, IL-6-activated STAT3 plays a major oncogenic role through the regulation of cell survival and proliferation." (PMID 32041604, 2020). "Oncogenic transcription factor STAT3 (Signal transducer and activator of transcription 3) involves in the development of hematological malignancies in multiple myeloma." (PMID 33260759, 2020).
multiple myeloma (continued). "In another study, celastrol inhibited STAT3 phosphorylation and STAT3-mediated IL-17 expression, and T-helper 17 (Th17) differentiation and proliferation in multiple myeloma cells." (PMID 32545187, 2020). "The phosphorylation of STAT3 was inhibited by auranofin through IL-6, leading to down-regulation of the anti-apoptotic proteins Mcl-1 and apoptosis of myeloma cells." (PMID 32695747, 2020). "IL-6 has a role in the development of multiple myeloma, as demonstrated by its ability to induce apoptosis by blocking the IL-6R/STAT3 pathway in vitro and the resistance of the IL-6 -/- mouse to the induction of plasmacytoma." (PMID 32283655, 2020). "This compound also inhibits multiple myeloma cell proliferation and induces apoptosis by suppressing STAT3 and STAT5 activation." (PMID 32041350, 2020). "Taken together, these findings substantiate a tight interplay of STAT3 and STAiR18, resulting in persistent survival of multiple myeloma cells." (PMID 32041604, 2020). "Cladribine, in combination with bendamustine or STAT3 inhibitor, exhibited inhibitory activity in multiple myeloma cells 52,53." (PMID 32624694, 2020). "It impaired the advancement of multiple myeloma xenograft tumors in male thymic mice by suppressing STAT3 activation by inactivating JAK1 and c-Srcin in various preclinical cancer models." (PMID 32545187, 2020). "In a previous publication, we further demonstrated that the induction of STAiR18 depends on STAT3 as STAT3 knockdown reduced STAiR18 expression in INA-6 multiple myeloma cells." (PMID 32041604, 2020). "The growth of human multiple myeloma cells was inhibited by resveratrol to overcome the chemoresistance by suppressing both the inducible and constitutive activation of STAT3, resulting in downregulation of antiapoptotic gene expressions." (PMID 32545187, 2020). "In human multiple myeloma (U266) cells, bergamottin has been found to suppress a constitutive activation of STAT3." (PMID 32545187, 2020). "Unlike resveratrol, curcumin blocked STAT3 phosphorylation, thereby blocking STAT3 dimer translocation from cytoplasm into the nucleus of human multiple myeloma cells." (PMID 32545187, 2020). "In human multiple myeloma cells, it suppressed the constitutive activation of STAT3 phosphorylation at tyrosine 705 residue." (PMID 32545187, 2020). "In multiple myeloma cells, it restrained the constitutive and IL-6-induced activation of STAT3 through inactivation of JAK1 and c-Src in a concentration-dependent fashion." (PMID 32545187, 2020). "A recent study showed that B7-H3 was involved in the activation of JAK2/STAT3 via redox-mediated oxidation and activation of Src in multiple myeloma cells." (PMID 32127943, 2020). "The antimalarial drug, pyrimethamine, has been described as an STAT3 inhibitor and a myeloma growth inhibitor." (PMID 32545187, 2020). "It was reported that auranofin inhibited IL-6-induced activation of JAK2/STAT3 signaling pathway and activation of NF-κB in human multiple myeloma cell line (U266, RPM8226, and IM9)." (PMID 32695747, 2020). "Constitutive activation of STAT3 has been described in hematopoietic disorders such as myeloma, Hodgkin lymphoma, anaplastic large cell lymphoma (ALK), angioimmunoblastic T cell lymphoma, adult T cell lymphoma/leukemia, and mantle lymphoma." (PMID 33158194, 2020). "In the myeloma cells and the myeloma cell lines obtained from patients, STAT3 has been seen to be active, yet it remains inactive in the plasma cells obtained from healthy individuals." (PMID 32679860, 2020). "STAT3 is an oncoprotein which has been shown to contribute to drug resistance in multiple myeloma (MM)." (PMID 30791634, 2019). "Formononetin has been found to suppress fibroblast growth factor 2 (FGF2)-induced STAT3 activation, successfully suppressing multiple myeloma, leukemia, lymphoma and solid tumors that display constitutive STAT3 activation." (PMID 31052435, 2019).
multiple myeloma (continued). "The interaction between IL-6 and IL-6R was shown to induce antiapoptotic effects on human esophageal carcinoma and multiple myeloma through the phosphorylation of gp130 and STAT3." (PMID 31252615, 2019). "The first direct link between STAT family proteins and carcinoma in human derived from research works that demonstrate that constitutively activated STAT3 is crucial for the carcinogenesis of head and neck cancer and multiple myeloma cells." (PMID 30847297, 2019). "Remarkably, a previous study revealed that RMP mediated the chemoresistance of multiple myeloma through NF-κB/IL-6/STAT3 signaling pathway." (PMID 31754340, 2019). "Optimising the pharmacokinetic profiles of novel STAT3 inhibitors and identifying how best to combine these agents with existing anti-myeloma therapy are key questions to be addressed in future clinical trials." (PMID 31130718, 2019). "Constitutive and sustained activation of STAT3 has been observed in many human malignancies including multiple myeloma, leukemia, lymphoma, and solid tumors." (PMID 31058086, 2019). "The plant derived triterpenoid asiaticoside was shown to exert anti myeloma effects through induction of autophagy and activation of caspases in addition to reducing STAT3 phosphorylation." (PMID 31130718, 2019). "IL-6 autocrine or paracrine loops was recognized as source for composition of STAT3 activity in myeloma and prostate malignant cell lines." (PMID 30847297, 2019). "Aberrant activation of signal transducer and activator of transcription 3 (STAT3) plays a critical role in the proliferation and survival of multiple myeloma." (PMID 30302278, 2018). "Recruitment of SMRT associated with HDAC by STAT3 leads to the transcriptional inactivation of STAT3 and consequent downregulation of IL-6-mediated multiple myeloma cell growth and gene expression." (PMID 29728695, 2018). "Bone marrow stromal cells (BMSCs) were reported to protect myeloma cells from cytostatic compounds through activating STAT3 cascade." (PMID 30302278, 2018). "leukemia, lymphoma and myeloma, and briefly highlights the potential therapeutic approaches developed against STAT3 activation pathway." (PMID 30217007, 2018). "Decursin enhanced caspase-9-mediated apoptosis in doxorubicin-treated multiple myeloma cells, via the mTOR and STAT3 pathways and other reports showed that decursin increased caspase-8-mediated apoptosis by increasing TRAIL sensitivity." (PMID 30155480, 2018). "Another study further demonstrated that GS inhibited the constitutive activation of STAT3 in U266 myeloma cells in a dose- and time-dependent manner." (PMID 30217007, 2018). "14-3-3ζ protein interacts with the phosphorylated Ser727 of STAT3 in multiple myeloma cells and prevents the dephosphorylation of this critical residue by protein phosphatase 2A (PP2A)." (PMID 29914167, 2018). "For example, curcumin has been shown to inhibit IL-6-induced STAT3 phosphorylation and consequent STAT3 nuclear translocation in multiple types of myeloma cell lines." (PMID 28204880, 2018). "It has been demonstrated to have a STAT3 inhibitory effect in various cell types including multiple myeloma (MM) cells." (PMID 30217007, 2018). "Altogether, our data indicates that the potential application of icariin as a STAT3 blocker in myeloma therapy." (PMID 29899697, 2018). "TQ also found to impede constitutive and IL-6-inducible STAT3 phosphorylation in U266 multiple myeloma cells, as well as inhibit c-Src and JAK-2 activation." (PMID 28983249, 2017). "The current study revealed that Reelin/FAK/Syk/Akt and STAT3 pathways in myeloma cells promoted HIF1α expression and cell glycolysis." (PMID 28345605, 2017). "Interleukin-6 (IL-6)-activated Signal Transducer and Activator of Transcription 3 (STAT3) facilitates survival in the multiple myeloma cell line INA-6 and therefore represents an oncogenic key player." (PMID 28801664, 2017).
multiple myeloma (continued). "Overall, GAC 17:1 was found to abrogate STAT3 signaling pathway and thus exert its anticancer effects against multiple myeloma cells." (PMID 28208828, 2017). "Among STAT family members, STAT3 in particular is often persistently activated in various human cancer cell lines such as multiple myeloma, leukemia, lymphoma, and solid tumors." (PMID 28208828, 2017). "Taken together, we discovered and described five lncRNAs, termed STAiRs, which are induced by IL-6-activated STAT3 in INA-6 multiple myeloma cells." (PMID 28801664, 2017). "IL-10 growth factor is produced by the myeloma cells of about half of these patients, and induces abnormal continuous STAT3 activation in malignant cells." (PMID 27418139, 2017). "Sustained activation of JAK/STAT3 signaling pathway is classically described in Multiple Myeloma (MM)." (PMID 28369102, 2017). "Our data further support the view that lncRNAs contribute to STAT3-dependent tumorigenesis in multiple myeloma as well as in other cancer types." (PMID 28801664, 2017). "The IL6/STAT3 activation enhances myeloma cell survival through the activation of anti-apoptotic genes, Mcl-1, Bcl-XL and c-Myc oncogene." (PMID 28458781, 2017). "In previous studies we identified microRNA-21 as a STAT3 target gene with strong anti-apoptotic potential, suggesting that noncoding RNAs have an impact on the pathogenesis of human multiple myeloma." (PMID 28801664, 2017). "IL-6, a growth factor for multiple myeloma cells, is overexpressed in various cancers and is a potent inducer of STAT3." (PMID 28208828, 2017). "IL-6 was also found to act on neuroblastoma and multiple myeloma cells within the bone marrow by increasing cell proliferation and survival through activation of the signal transducer and activator of transcription 3 (STAT3) pathway." (PMID 28148268, 2017). "The up-regulation of miR-21 is shown to facilitate the activation of IL6-JAK-STAT pathway and STAT3, which is a major mediator of growth, proliferation and survival of myeloma cells conferred by bone marrow microenvironment." (PMID 28458781, 2017). "We found that GAC 17:1 inhibited both constitutive and IL-6-inducible STAT3 activation in multiple myeloma cells along with the abrogation of c-Src and JAK2 activation and the induction of PTEN and SHP-1 proteins." (PMID 28208828, 2017). "clearly highlighted the potential of UA to modulate the STAT3 signaling cascade in multiple myeloma." (PMID 28801966, 2017). "Our investigation on multiple myeloma cell lines indicates that Reelin-induced activation of integrin β110 and its downstream FAK/Syk results in the phosphorylation of both PI3K/Akt/mTOR and STAT3, providing combinatorial cues for myeloma cell proliferation." (PMID 28345605, 2017). "We determined effect of GAC 17:1 using multiple myeloma U266 cells in which STAT3 has been found to be constitutively activated." (PMID 28208828, 2017). "Taken together, our study reveals a number of STAT3-induced lncRNAs suggesting that the interplay between the coding and noncoding worlds represents a fundamental principle of STAT3-driven cancer development in multiple myeloma and beyond." (PMID 28801664, 2017). "MiR-21 promotes STAT3 phosphorylation through targeting the protein inhibitor of activated STAT3 (PIAS3) in multiple myeloma cells." (PMID 28752208, 2017). "The FAK/Syk/Akt/mTOR and STAT3 signaling pathways activated by Reelin significantly contribute to the increase in myeloma cell proliferation and glycolysis." (PMID 28345605, 2017). "In this study, we introduce STAiRs, five IL-6/STAT3-induced long ncRNAs in INA-6 multiple myeloma cells." (PMID 28801664, 2017). "We determined the anti-tumor mechanism of GAC 17:1 with respect to its effect on STAT3 signaling pathway in multiple myeloma cell lines." (PMID 28208828, 2017).
multiple myeloma (continued). "Enhanced IL-10 levels foster phosphorylation of the survival molecule STAT-3 as well as modulation of proteasomal activity and shedding of immunoglobulins, contributing to myeloma survival under treatment." (PMID 27732933, 2016). "Rhee and co-worker have reported that ergosterol peroxide inhibited the signaling pathway proteins JAK2/STAT3, which are important in angiogenesis, and exerted anti-tumor activity in multiple myeloma U266 cells." (PMID 27058618, 2016). "STAT3 is overexpressed in a broad range of cancers including hematological malignancies, including leukemia, lymphoma and multiple myeloma (MM)." (PMID 26814430, 2016). "The expression of cyclinD1, phosphorylated AKT and STAT3 proteins in myeloma cells were increased when co-cultured with adipocytes, whereas the percentage of phosphorylated proteins decreased when using anti-lepin receptor antibody." (PMID 27863383, 2016). "The oncogenic STAT3 signaling pathway is emerging as a promising target for the treatment of multiple myeloma (MM)." (PMID 26814430, 2016). "In the IL-6-dependent human myeloma cell line U266, IL-6 signals through Janus kinases to the activate STAT3, which in turn up-regulates anti-apoptotic factors, and promotes the survival of tumor cells." (PMID 26972355, 2016). "Dietary gamma-tocotrienol inhibited both induced and constitutive activation of STAT3 in multiple myeloma and prostate cancer cell lines." (PMID 26881027, 2016). "Collectively, these data indicate that PRL-3 influences the phosphorylation of STAT3, a signaling pathway important for myeloma cell survival." (PMID 27036022, 2016). "STAT3 has a significant function in blocking apoptosis and keeping cells alive during inflammatory responses, improving the survival and proliferation of myeloma." (PMID 25942007, 2015). "Numerous cytokines induce expression of members of the anti-apoptotic regulator Bcl-2 family of proteins and STAT3 represses apoptosis in human myeloma cells by stimulating expression of Bcl-XL." (PMID 26464811, 2015). "Here, we show that IL-6-induced STAT3 tyrosine phosphorylation is significantly enhanced in CD45+ myeloma cells in comparison with CD45- myeloma cells." (PMID 25781885, 2015). "Previous studies reported that Icaritin is able to reduce phosphorylation of Stat3 (Y705) in chronic myeloid leukemia and multiple myeloma." (PMID 26376676, 2015). "Icaritin suppressed the expression of p-JAK2, p-STAT3 as well as VEGF in myeloma tissue evaluated by immunohistochemistry and western blot, which were consistent with the results of in vitro experiments." (PMID 25865044, 2015). "STAT3 is often constitutively activated in many human cancer cells such as multiple myeloma, leukemia, lymphoma, and solid tumors, which confers myeloma cells resistance to apoptosis through regulation of the anti-apoptotic protein Bcl-xL." (PMID 25865044, 2015). "We further evaluated the potential effects of icaritin on the status of JAK2 and STAT3, which are frequently activated in myeloma cells." (PMID 25865044, 2015). "It is also worth noting that STAT3 activation is important for the survival of multiple myeloma cells." (PMID 24600453, 2014). "Various types of cancer, including head and neck cancers multiple myeloma, lymphomas, and leukemia, also have constitutively active STAT3." (PMID 24655440, 2014). "With this, inhibition of STAT3 with compounds such as curcumin, atiprimod, and the JAK2 kinase inhibitor AG490 are associated with inhibition of IL-6-induced myeloma survival in vitro." (PMID 24803933, 2014). "A research study reported that the inhibition of the activation of upstream JAK1, JAK2, and c-Src kinases suppressed the downstream STAT3 in human multiple myeloma cells." (PMID 25405202, 2014). "Thymoquinone inhibited proliferation, induced apoptosis, and chemosensitized human multiple myeloma cells through suppression of the signal transducer and activator of transcription 3 (STAT3) activation pathway." (PMID 25401162, 2014).